RNU7-185P (RNA, U7 small nuclear 185 pseudogene)
Gene: Small nuclear RNA gene on chromosome 9 (8,797,135 to 8,797,194, forward strand). Ensembl gene ENSG00000239102.
Homologues: Orthologues: chimpanzee U7 (100% identical). Paralogues in human: RNU7-7P (83% identical), RNU7-28P (82% identical), RNU7-147P (80% identical), RNU7-18P (80% identical), RNU7-22P (80% identical), RNU7-40P (80% identical), RNU7-41P (80% identical), RNU7-6P (80% identical), RNU7-74P (80% identical), RNU7-106P (78% identical), RNU7-10P (78% identical), RNU7-11P (78% identical), and 142 more.